NETO2 (neuropilin and tolloid like 2)
Diseases named in the same sentence as NETO2 in open-access papers (continued):
Sharing a sentence is not in itself a finding about the gene and the disease.
tumor (continued). "Moreover, NETO2, an important paralog of NETO1, has been investigated as a tumour‐promoting molecule in a variety of cancers and NETO2 expression has been found to have a significant correlation with poor prognostic results in these cancers." (PMID 32638511, 2020). "High expression of NETO2 protein was significantly correlated with poor tumor differentiation (p = 0.013), advanced local invasion (p = 0.049), increased lymph node metastasis (p = 0.009), advanced TNM stage of the disease (p = 0.041), and increased death rate of patients (p = 0.001)." (PMID 26699544, 2015). "Our results demonstrated that increased expression of NETO2 was correlated with tumor progression and might serve as an independent unfavorable prognostic indicator for patients with CRC." (PMID 26699544, 2015). "Our findings suggest that NETO2 upregulation could serve as a potential biomarker for the prediction of advanced tumor progression and unfavorable prognosis in patients with CRC." (PMID 26699544, 2015). "Thus, NETO2 is a tumor-promoting factor in GC and may serve as a novel prognostic indicator as well as a potential therapeutic target for GC." (PMID 30770791, 2019). "In oesophageal squamous cell carcinoma, exosome lncRNA FAM225A upregulates the expression of NETO2 and FOXP1 by absorbing miR‐206, participating in progression and angiogenesis of tumor." (PMID 38652109, 2024). "Although NETO2 and SAPCD2 have been reported to be involved in angiogenesis in different tumor types, the potential roles of these two genes in PCa were not elucidated." (PMID 34540835, 2021). "In our analysis eight new candidate tumor suppressor genes were identified, OXSR1 (3p22.2), BSG(19p13.3), NT5E(6q14.3), PLEKHG7(12q22), CMTM8(3p22.3), NETO2(16q12.1), ODZ3(4q35.1) and ERBB4(2q34)." (PMID 25551557, 2014). "Overexpression of NETO2, VCAN, and GBP2 in tumor tissues compared to normal tissues were observed in 93.75% (15/16), 93.75 (15/16), and 87.5% (14/16), respectively." (PMID 24783204, 2014). "Three genes, including NETO2, GBP2, and VCAN, showed consistent high expression across these 90 tumor samples." (PMID 24783204, 2014). "Silencing or knockout of NETO2 could block the effect of sLRIG3, which inhibited the M2-like polarity transformation of TAMs and promoted GBM tumor growth." (PMID 36639372, 2023). "In contrast, we failed to observe any significant correlations between the NETO2 mRNA level and tumor stage, as well as differentiation that can be explained by the difference of the studied cohorts." (PMID 33362854, 2020). "Besides the known tumor suppressor genes DOCK5 and PTEN, genes OXSR1, BSG, NT5E, PLEKHG7,CMTM8, NETO2, ODZ3, and ERBB4 adhered to our criteria and were qualified as novel candidate tumor suppressor genes." (PMID 25551557, 2014). "Neuropilin and tolloid-like 2 (NETO2) is a common overexpressed gene LC, which may also be related to HTLV-1 infection, regulating aneuploidy, metastasis, cell proliferation, apoptosis, tumor growth, and ERK phosphorylation." (PMID 41440381, 2025). "Notably, as these tumor tissues were not isolated by laser capture microdissection technology, the inclusion of non-epithelial cells not expressing NETO2 in PCR and Western blot experiments may interfere with the evaluation of NETO2 expression in CRC and adjacent normal tissues." (PMID 26699544, 2015).
cancer (12 papers, 2015 to 2025). A tumor composed of atypical neoplastic, often pleomorphic cells that invade other tissues. "Neuropilin and tolloid-like 2 (NETO2) protein coding genes have been associated with various human cancers." (PMID 33390848, 2021). "Recently studies have also linked NETO2 to an oncogene in various types of cancers." (PMID 33390848, 2021). "Although NETO2 was originally thought to be a neuron-specific protein 13, increasing evidence indicates NETO2 expression is also detectable in several types of cancers." (PMID 33390848, 2021). "Through a series of functional analyses (in vitro), we verified the pro-cancer abilities of NETO2 and SAPCD2, which provided a new approach for further study on the mechanism in PCa." (PMID 34540835, 2021). "Using qPCR, we analyzed the relative NETO2 mRNA level in sets of breast (n = 32), prostate (n = 40), and colorectal (n = 74) cancer samples." (PMID 33362854, 2020). "The staining of NETO2 was significantly higher in cancer tissues and metastatic lymph nodes than that in normal gastric mucosa (p < 0.0001)." (PMID 30770791, 2019). "Aberrant expression of neuropilin and tolloid-like 2 (NETO2) has been observed during the progression of some human carcinomas." (PMID 30770791, 2019). "Upregulation of NETO2 enhances cancer progression by activating PI3K/AKT- and ERK/MAPK-dependent cascades and downstream transcription factors such as NF-κB, Snail, and Nrf2, thereby promoting epithelial–mesenchymal transition, proliferation, migration, and invasion." (PMID 41373864, 2025). "The function of NETO2 in tumorigenesis remains unclear; however, our findings and those obtained in previous studies indicate its participation in cancer-related signaling pathways." (PMID 33362854, 2020). "Furthermore, the participation of NETO2 has been revealed in the Jak-STAT signaling pathway during cancer." (PMID 33362854, 2020). "Increased expression of the NETO2 gene has been observed in proliferating infantile hemangiomas, hepatocellular and nasopharyngeal carcinomas, as well as in renal, lung, colorectal, gastric, and pancreatic cancers." (PMID 33362854, 2020). "Upregulation of NETO2 gene was also detected in several cancer types." (PMID 29297384, 2017). "In addition, NETO2 expression was upregulated in multiple cancer and was correlated with the prognosis of cancer patients, which suggests that NETO2 may affect the progression of different cancer through different mechanisms." (PMID 36639372, 2023). "Since the MAPK/ERK kinase, (MEK)-ERK, and PI3K/AKT pathways play important roles in cancer cell proliferation and metastasis, we assessed the phosphorylation of ERK1/2 PI3K AKT in cells with knock down and overexpression of NETO2." (PMID 33390848, 2021). "Moreover, we revealed a high similarity between human NETO2 and its ortholog in fish Nothobranchius furzeri, which demonstrate the shortest captive lifespan for a vertebrate (3 months), a novel model for investigating aging and aging-related pathologies, including cancer." (PMID 33362854, 2020). "The role and clinical relevance of NETO2 in cancers have not been well illustrated." (PMID 30770791, 2019). "Since the increase in NETO2 expression could also be the result of other factors that lead to cancer progression, rather than NETO2 overexpression being a contributing factor in cancer progression." (PMID 26699544, 2015).
NETO2 also shares sentences with these, for which no sentence is quoted: colon cancer (2 papers); esophageal squamous cell carcinoma (2); nasopharyngeal carcinoma (2); pancreatic cancer (2); bowel obstruction (1); Hydrocephalus (1); infection (1); lung adenocarcinoma (1); myocardial infarction (1); posttraumatic stress disorder (1); renal clear cell carcinoma (1); Seizure (1).